CD4 (CD4 molecule)
Description:
Integral membrane glycoprotein that plays an essential role in the immune response and serves multiple functions in responses against both external and internal offenses. In T-cells, functions primarily as a coreceptor for MHC class II molecule:peptide complex. The antigens presented by class II peptides are derived from extracellular proteins while class I peptides are derived from cytosolic proteins. Interacts simultaneously with the T-cell receptor (TCR) and the MHC class II presented by antigen presenting cells (APCs). In turn, recruits the Src kinase LCK to the vicinity of the TCR-CD3 complex. LCK then initiates different intracellular signaling pathways by phosphorylating various substrates ultimately leading to lymphokine production, motility, adhesion and activation of T-helper cells. In other cells such as macrophages or NK cells, plays a role in differentiation/activation, cytokine expression and cell migration in a TCR/LCK-independent pathway. Participates in the development of T-helper cells in the thymus and triggers the differentiation of monocytes into functional mature macrophages. (Microbial infection) Primary receptor for human immunodeficiency virus-1 (HIV-1). Down-regulated by HIV-1 Vpu. Acts as a receptor for Human Herpes virus 7/HHV-7.
Synonyms: T4; Leu-3; CD4mut; IMD79; OKT4D
Tractability: Small molecule: a structure with a bound ligand is known. Antibody: an approved drug acts on it; UniProt places it where antibodies can reach, with high confidence; its Gene Ontology location is reachable by antibodies, with high confidence; UniProt predicts a signal peptide or a membrane-spanning region; the Human Protein Atlas places it where antibodies can reach. PROTAC: ubiquitination databases record sites on it; its protein half-life has been measured; a small molecule that binds it is known. Other modalities: a drug acting on it is in phase 2 or 3 trials.
Target class: Surface antigen
Gene: Protein-coding gene on chromosome 12 (6,786,858 to 6,820,807, forward strand). Ensembl gene ENSG00000010610.
Subcellular location: Cell membrane
Subcellular location (Human Protein Atlas): Plasma membrane
Pathways (Reactome):
Immune System: Alpha-defensins; Co-inhibition by PD-1; Downstream TCR signaling; Generation of second messenger molecules; Other interleukin signaling; Phosphorylation of CD3 and TCR zeta chains; Translocation of ZAP-70 to Immunological synapse
Disease: Binding and entry of HIV virion; Nef Mediated CD4 Down-regulation; Vpu mediated degradation of CD4
Vesicle-mediated transport: Cargo recognition for clathrin-mediated endocytosis; Clathrin-mediated endocytosis
Gene Ontology:
Molecular function: coreceptor activity; enzyme binding; identical protein binding; interleukin-16 binding; interleukin-16 receptor activity; lipid binding; MHC class II protein binding; MHC class II protein complex binding; protein binding; protein homodimerization activity; protein kinase binding; protein tyrosine kinase binding; virus receptor activity; zinc ion binding; extracellular matrix structural constituent; signaling receptor activity; signaling receptor binding; transmembrane signaling receptor activity; immunoglobulin binding
Biological process: cellular response to granulocyte macrophage colony-stimulating factor stimulus; interleukin-15-mediated signaling pathway; macrophage differentiation; maintenance of protein location in cell; positive regulation of monocyte differentiation; regulation of T cell activation; symbiont entry into host cell; T cell differentiation; T cell receptor signaling pathway; T cell selection; cell surface receptor protein tyrosine kinase signaling pathway; cell surface receptor signaling pathway; enzyme-linked receptor protein signaling pathway; helper T cell enhancement of adaptive immune response; immune response; leukocyte chemotaxis; positive regulation of inflammatory response; positive regulation of interleukin-2 production; signal transduction; T cell activation; cell adhesion; cellular response to ionomycin; positive regulation of calcium ion transport into cytosol; positive regulation of immune system process; positive regulation of multicellular organismal process; and 5 more
Cellular component: external side of plasma membrane; membrane raft; plasma membrane; clathrin-coated endocytic vesicle membrane; early endosome; endoplasmic reticulum membrane; T cell receptor complex; cell surface; endoplasmic reticulum lumen; membrane
Genetic constraint (gnomAD): Loss-of-function variants: 24 observed, 50.18 expected, observed/expected ratio (o/e) 0.48, 90% interval 0.34 to 0.67. The upper end of that interval is the gene's LOEUF score, 0.67, which puts it in group 2 of 6, group 1 being the genes least tolerant of losing a copy. Missense variants: 454 observed, 563.98 expected, observed/expected ratio (o/e) 0.81, 90% interval 0.75 to 0.87. Synonymous variants: 207 observed, 230.05 expected, observed/expected ratio (o/e) 0.9, 90% interval 0.8 to 1.01.
Homologues: Orthologues: chimpanzee CD4 (99% identical), macaque CD4 (92% identical), dog CD4 (60% identical), pig CD4 (59% identical), rabbit CD4 (58% identical), mouse Cd4 (55% identical), rat Cd4 (54% identical), guinea pig Cd4 (52% identical), zebrafish cd4-1 (18% identical), zebrafish dicp3.1 (10% identical), zebrafish dicp1.16 (9% identical), zebrafish dicp3.3 (9% identical), and 6 more.
Diseases named in the same sentence as CD4 in open-access papers:
CD4 is named in the same sentence as 1,829 diseases in open-access papers, as found by Europe PMC text mining. Sharing a sentence is not in itself a finding about the gene and the disease. The quoted sentences say what the papers report.
AIDS (3,603 papers, 2004 to 2026). A syndrome resulting from the acquired deficiency of cellular immunity caused by the human immunodeficiency virus (HIV). "This can provide valuable insights into disease progression and risk assessment in terms of viral load, CD4 cell count, treatment initiation, treatment adherence, hospitalization, acquired immunodeficiency syndrome diagnosis, quality of life and mental health." (PMID 41473774, 2026). "Approximately 10–40% of patients with acquired immune deficiency syndrome (AIDS) fail to restore the number of CD4+ T cells after antiretroviral therapy (ART)." (PMID 40996268, 2025). "One of the indications of infection is the continuous destruction of CD4+ T cells, which eventually collapses the human immune system leading to the acquired immune deficiency syndrome (AIDS) and increased mortality." (PMID 40574839, 2025). "Some people with Human Immunodeficiency Virus (HIV) on effective antiretroviral therapy have persistent low lymphocyte CD4 counts and remain at an increased risk of Acquired Immunodeficiency Syndrome (AIDS)." (PMID 40003876, 2025). "In HIV patients, Serratia marcescens infection is usually associated with low CD4+ counts of less than 70 cells/ml and an acquired immunodeficiency syndrome (AIDS) stage (as per CDC, AIDS or stage 3)." (PMID 41567916, 2025). "HIV attacks the human immune system by destroying CD4+ T lymphocytes, leading to immune system collapse, which can progress to acquired immune deficiency syndrome (AIDS) and result in various severe opportunistic infections and tumours." (PMID 39973397, 2025). "This study, published in the Journal of Acquired Immune Deficiency Syndromes, focuses on the prognostic value of the CD4/CD8 ratio in HIV/AIDS patients and how it relates to disease progression." (PMID 38428854, 2024). "In patients with acquired immune deficiency syndrome (AIDS) who have a CD4 count <100 cells/μL, toxoplasmosis reactivated in approximately 30% of the patients who were seropositive and not undergoing antiretroviral therapy (ART)." (PMID 38950027, 2024). "The use of immunophenotyping as a diagnostic tool was first popularized in the early 1980 s when it was discovered that acquired immunodeficiency syndrome (AIDS) was associated with a decrease in cluster of differentiation 4 (CD4+) T-cells." (PMID 39430110, 2024). "The human immunodeficiency virus (HIV) can impair the immune system by targeting the CD4+ T lymphocyte cells, which causes the acquired immune deficiency syndrome (AIDS)." (PMID 38674726, 2024). "Over time, HIV infection causes a reduction in host CD4+ T cells and immunological defects that can lead to acquired immune deficiency syndrome (AIDS)." (PMID 38587380, 2024). "Human immunodeficiency virus/acquired immunodeficiency syndrome (HIV/AIDS) is an endemic chronic disease which is characterized with progressive depletion of CD4 T cells and increased susceptibility to opportunistic infections." (PMID 38654196, 2024). "The human immunodeficiency virus (HIV) primarily targets CD4+ T cells, leading to acquired immune deficiency syndrome (AIDS) and resulting in an excessive inflammatory response." (PMID 39335573, 2024). "The primary risk factor for CM is acquired immunodeficiency syndrome, particularly in individuals with a CD4 count below 100 mm3." (PMID 39450395, 2024). "HIV causes human immune subversion and continuous loss of CD4+ T-helper cells, impairing the immune system and leading to acquired immunodeficiency syndrome (AIDS)." (PMID 36839551, 2023). "Acquired immunodeficiency syndrome (AIDS) is caused by the Human Immunodeficiency Virus (HIV) which suppresses the human CD4+ T-cell immune system supporting opportunistic infections." (PMID 37896769, 2023). "The untreated human immunodeficiency virus (HIV), a lentivirus species that attacks immune cells (CD4+ T cells), causes acquired immunodeficiency syndrome (AIDS)." (PMID 37765399, 2023).
AIDS (continued). "Acquired immune deficiency syndrome (AIDS) is a malignant infectious disease caused by human immunodeficiency virus (HIV) invading CD4+ cells, resulting in imbalance and damage to human immune function, in turn causing serious harm to the human body." (PMID 36033568, 2022). "HIV attacks the infected host’s CD4+ T cells, resulting in acquired immune deficiency syndrome (AIDS) which neutralizes the host’s immune response, leaving the host vulnerable to secondary infections." (PMID 36135023, 2022). "HIV increases the risk of tuberculosis disease progression, while M. tuberculosis reduces CD4 + T-cells recovery and increases acquired immune deficiency syndrome progression." (PMID 35204544, 2022). "The chronic decline in CD4 T cells caused by HIV infection leads to acquired immunodeficiency syndrome (AIDS, also known as stage 3 HIV)." (PMID 36145313, 2022). "HIV-1 infection is marked by the progressive depletion of peripheral CD4+ T cells and is the causative factor of acquired immunodeficiency syndrome (AIDS)." (PMID 35890062, 2022). "HIV-1 infection leads to progressive loss of CD4+ T cells that results in the development of acquired immunodeficiency syndrome (AIDS)." (PMID 36175869, 2022). "Among patients with HIV, the median CD4 count was 52 cell/mm3 (range 4-226), and 88.4% had a history of opportunistic infections of acquired immune deficiency syndrome (AIDS)." (PMID 33897776, 2021). "The hallmark of HIV infection is the progressive loss of total CD4+ T cells and dysregulation of homeostasis, later culminating in acquired immune deficiency syndrome (AIDS)." (PMID 34721397, 2021). "Human immunodeficiency viruses (HIVs) are retroviruses that replicate effectively in human CD4+ cells and cause the development of acquired immune deficiency syndrome (AIDS)." (PMID 34566998, 2021). "HIV-1 is a type I enveloped virus that infects CD4+T cells and destroys the human immune system, resulting in acquired immune deficiency syndrome (AIDS)." (PMID 33807292, 2021). "HIV-1 is a lentivirus that infects CD4+ human immune cells, such as T cells and macrophages, and is the causative agent of acquired immune deficiency syndrome (AIDS)." (PMID 34937567, 2021). "The result is a gradual decline of host CD4+ T cells leading to full blown acquired immune deficiency syndrome (AIDS) over time." (PMID 34017334, 2021). "HIV-1 is the principal variant that causes chronic disease because it decreases the body’s immune cell count (CD4 cells), leading to acquired immunodeficiency syndrome (AIDS), which predisposes one to life-threatening opportunistic infections." (PMID 34681233, 2021). "Compared with immune responders (IRs), in whom both CD4+ T cell counts and function are restored, INRs remain at greater risk of developing non-acquired immunodeficiency syndrome (AIDS)-related-events, with the accompanying increased morbidity and mortality." (PMID 34887859, 2021). "The acquired immune deficiency syndrome (AIDS) appeared to have a marked reduction in CD4+ cell numbers, enhanced B-cell proliferation, and hypergammaglobulinemia." (PMID 34595076, 2021). "Elimination of CD4+ T cells by HIV is a hallmark of acquired immune deficiency syndrome (AIDS), resulting in increased susceptibility to opportunistic infections and viral-associated cancers." (PMID 33329545, 2020). "Human immunodeficiency virus (HIV-1) is a retrovirus that infects CD4+ T-lymphocytes and macrophages, leading to a gradual loss of CD4+ cells and subsequent immunodepression termed acquired immunodeficiency syndrome (AIDS)." (PMID 33352061, 2020). "This would explain the improvement of the CD4 T cell counts in acquired immune deficiency syndrome (AIDS) patients following a CoQ10 supplementation treatment." (PMID 33182646, 2020). "This includes severe combined immune deficiency, isolated CD4+ T lymphocyte deficiency, and acquired immunodeficiency syndrome induced by human immunodeficiency virus, which destroys CD4+ T lymphocytes." (PMID 32570978, 2020).
AIDS (continued). "Human Immunodeficiency Virus infection is characterised by a depletion of cell-mediated immunity via progressive loss of CD4+ T cells, leading to increased risk of opportunistic infections and the Acquired Immunodeficiency Syndrome (AIDS)." (PMID 33141357, 2020). "Glicine-tryptophan-glicine or glicine-proline-glicine motif according time of time of acquired immune deficiency, CD4 count, and human immunodeficiency virus viral load." (PMID 31335686, 2019). "Human immunodeficiency virus (HIV) infection is characterized by a progressive loss of CD4+ T lymphocytes, which leads to failure of the immune system and (if left untreated) to acquired immunodeficiency syndrome (AIDS)." (PMID 33324890, 2019). "Human immunodeficiency virus (HIV) infects CD4+ T cells and causes acquired immunodeficiency syndrome (AIDS)." (PMID 30862061, 2019). "Human immunodeficiency virus (HIV) infects CD4+ T cells, causing a progressive immunodeficiency in the absence of combination antiretroviral therapy (cART), resulting in the progression to acquired immune deficiency syndrome (AIDS)." (PMID 30400258, 2018). "Human immunodeficiency virus type 1 (HIV-1) is a very important global pathogen that preferentially targets CD4+ T cells and causes acquired immunodeficiency syndrome (AIDS) if left untreated." (PMID 30206166, 2018). "Human immunodeficiency virus type 1 (HIV-1) infects and progressively depletes CD4+ T cells, causing acquired immune deficiency syndrome (AIDS)." (PMID 29725337, 2018). "The use of live vaccines is contraindicated in HIV-infected adults, especially if the CD4+ count is below 200 cells/μL, and/or there is clinical evidence of acquired immune deficiency syndrome (AIDS)." (PMID 39449989, 2018). "Patients with HIV and acquired immunodeficiency syndrome (AIDS) with CD4 cell counts below 50 cells/microliter are at high risk for CMV infection involving multiple organs including the gastrointestinal tract." (PMID 28884052, 2017). "The natural history of HIV before antiretroviral therapy is represented by four stages: primary, CD4 cell count 200 cells μl−1 or greater, CD4 cell count less than 200 cells μl−1 before acquired immune deficiency syndrome (AIDS) diagnosis and AIDS." (PMID 28781386, 2017). "Human immunodeficiency virus type 1 (HIV-1) is the causative agent of acquired immunodeficiency syndrome and its infection leads to the onset of several disorders such as the depletion of peripheral CD4+ T cells and immune activation." (PMID 29379496, 2017). "The CD4 lymphocyte count of HIV-infected individuals is a significant predictor of HIV progression as well as acquired immune deficiency syndrome (AIDS)-associated mortality." (PMID 29100529, 2017). "In the 1980s and 90s, pneumocystosis predominantly developed in HIV-patients with low CD4+ T cell counts and was classified as an acquired immunodeficiency syndrome (AIDS)-defining disease, associated with a high mortality rate." (PMID 29202739, 2017). "CD4+ T-cell count ≤200/μL is defined as acquired immunodeficiency syndrome (AIDS) and highly susceptible to TB and opportunistic infections." (PMID 26959228, 2016). "Infection with human immunodeficiency virus type 1 (HIV-1) causes a progressive loss of CD4+ T cells that leads to the development of acquired immunodeficiency syndrome (AIDS)." (PMID 26247731, 2015). "When CD4+ cells drop to below 200 cells/ul, the infection is usually considered to enter the late stage, i.e., acquired immune deficiency syndrome (AIDS)." (PMID 26709961, 2015). "Altogether, these mechanisms entertain chronic viral replication and continuous depletion of CD4 T cells, leading to the dramatically enhanced susceptibility to opportunistic infections characteristic of the acquired immunodeficiency syndrome (AIDS)." (PMID 25400632, 2014).